MIR146A (microRNA 146a)
Synonyms: hsa-mir-146; hsa-mir-146a; MIRN146; MIRN146A; miR-146a; miRNA146A
Gene: MicroRNA gene on chromosome 5 (160,485,352 to 160,485,450, forward strand). Ensembl gene ENSG00000283733.
Gene Ontology:
Biological process: miRNA-mediated post-transcriptional gene silencing
Cellular component: RISC complex
Diseases named in the same sentence as MIR146A in open-access papers:
MIR146A is named in the same sentence as 15 diseases in open-access papers, as found by Europe PMC text mining. Sharing a sentence is not in itself a finding about the gene and the disease. The quoted sentences say what the papers report.
autoimmune disease (3 papers, 2014 to 2019). A disorder resulting from loss of function or tissue destruction of an organ or multiple organs, arising from humoral or cellular immune responses of the individual to their own tissue constituents. "The dynamic interactive roles of MIR146A could also be useful to investigate the relationship between AMD and the co-occurrence of late-onset disease conditions, especially cardiovascular diseases, autoimmune diseases, diabetes, chronic kidney disease, AD, and PD." (PMID 30934838, 2019).
asthma (1 paper, 2024). "The knockout MIR146a/b−/− mouse asthma model induced by HDM showed an increased number of B cells and strongly reduced numbers of Th2 cells in BALF compared with wild asthmatic mice." (PMID 38337625, 2024).
melanoma (1 paper, 2018). A malignant, usually aggressive tumor composed of atypical, neoplastic melanocytes. "In a bivariate analysis combining the nevus results with a recent melanoma GWAS meta-analysis (12,874 cases, 23,203 controls), SNPs near GPRC5A, CYP1B1, PPARGC1B, HDAC4, FAM208B, DOCK8, and SYNE2 reached global significance, and other loci, including MIR146A and OBFC1, reached a suggestive level." (PMID 30429480, 2018).
tumor (5 papers, 2014 to 2025). "MIR146A has been extensively studied in literature, mostly in association to tumor." (PMID 40201796, 2025). "It is possible that the reduction in activity associated with rs486907 may have differential effects in various tissue contexts, including tumor types, and when found in combination with other genetic variants, such as MIR146A rs2910164." (PMID 24699816, 2014). "Mir146a has been shown to play either an oncogenic or tumor suppressor role, depending on the cancer type and cellular context." (PMID 37239070, 2023). "Conversely, in the absence of HER2-signaling-phosphorylated Sp1, HDACs tend to combine with S100 and upregulate the expression of FAS and MIR146A genes, contributing to tumor suppression." (PMID 37174034, 2023). "The resulting Sp1-HDAC1 complex deacetylates H3K56 (histone H3 lysine 56), silences FAS and MIR146A genes and upregulates miR-146a targets such as interleukin-1 receptor-associated kinase 1 (IRAK1) and the chemokine receptor CXCR4, and ultimately promotes tumor invasion, proliferation, and survival." (PMID 37174034, 2023).
cancer (3 papers, 2022 to 2024). A tumor composed of atypical neoplastic, often pleomorphic cells that invade other tissues. "GSEA also uncovered that MUC1-C and XIST regulate the MIR146A TARGETS gene signature, which like miR-21, miR-146a associates with inflammation and cancer." (PMID 38740827, 2024).
infection (1 paper, 2021). The state of being infected such as from the introduction of a foreign agent such as serum, vaccine, antigenic substance or organism. "We found an increased total number of cells in the airways, including neutrophils, DCs, and T cells, as well as enhanced expression of Cxcl1, S100a8, and S100a9 after RV‐A1b infection in Mir146a/b−/‐ mice compared to wt mice." (PMID 34185416, 2021). "Similar to in vitro results in HBECs, RV‐A1b infection stimulated the expression of miR‐146a/b in wt mouse lungs, while no miR‐146a/b was detected in Mir146a/b−/− mice." (PMID 34185416, 2021).
inflammation (1 paper, 2021). Aberrant reaction of the microcirculation characterized by movement of fluid and leukocytes from the blood into extravascular tissues. "In line with results from the RV‐induced airway inflammation model, increased mRNA expression of Cxcl1, Cxcl2, and Ifitm1 in HDM‐stimulated Mir146a/b−/− splenocytes was detected." (PMID 34185416, 2021).
MIR146A also shares sentences with these, for which no sentence is quoted: lung carcinoma (2 papers); psoriatic arthritis (2); systemic lupus erythematosus (2); cardiovascular diseases (1); chronic kidney disease (1); diabetes (1); psoriasis (1); rheumatoid arthritis (1).